FGL2 (fibrinogen like 2)
Diseases named in the same sentence as FGL2 in open-access papers (continued):
Sharing a sentence is not in itself a finding about the gene and the disease.
liver diseases (5 papers, 2010 to 2024). "We recently reported that increased plasma levels of FGL2 in chronically infected HCV patients are associated with increased severity of liver disease and a poor outcome to anti-viral therapy." (PMID 24146739, 2013). "Recent research has highlighted the involvement of fibrinogen-like protein 1 (FGL1) and fibrinogen-like protein 2 (FGL2), both members of the FREPs family, in the regulation of various liver diseases." (PMID 38816776, 2024). "Recent studies have highlighted the involvement of fibrinogen-like proteins, specifically fibrinogen-like protein 1 (FGL1) and fibrinogen-like protein 2 (FGL2), in the regulation of various liver diseases." (PMID 38816776, 2024). "This review provides an overview of the current knowledge regarding the roles of FGL1 and FGL2 in liver disease." (PMID 38816776, 2024). "Soluble FGL2 levels were measured in different clinical subgroups of patients with HBV-related liver diseases and in healthy controls." (PMID 30419833, 2018). "Furthermore, it explores the potential benefits and challenges of targeting FGL1 and FGL2 for liver disease treatment and the prospects of fibrinogen-like proteins as biomarkers for liver disease, offering insights for future research in this field." (PMID 38816776, 2024). "Additionally, we discuss the potential of FGL1 and FGL2 as immunotherapeutic targets for various liver diseases." (PMID 38816776, 2024). "In an experimental model of fulminant hepatic failure (FHF) caused by MHV-3, increased plasma levels of FGL2 as well as increased frequencies of Treg, pre- and post- MHV-3 infection were shown to be predictive of disease susceptibility and severity of liver disease." (PMID 24146739, 2013). "The FGL2 gene and corresponding proteins (mFGL2 and sFGL2) may be a target for therapeutic intervention of HBV-related liver diseases." (PMID 30419833, 2018).
melanoma (4 papers, 2024 to 2025). A malignant, usually aggressive tumor composed of atypical, neoplastic melanocytes. "Further, exhausted CD8+ T cell-derived Fgl2 is associated with worsened mortality in human patients with melanoma." (PMID 38902261, 2024). "In humans, CD8+ T cell-derived Fgl2 is associated with poorer survival in patients with melanoma." (PMID 38902261, 2024). "In patients with melanoma, myeloid cells were a substantial source of Fgl2 compared with other sorted populations; this finding was consistent across 7 other cancer types." (PMID 40125553, 2025). "Here, we show that fibrinogen-like protein 2 (Fgl2) is elevated in the setting of melanoma in humans and mice and plays a functional role in inhibiting the CD8+ T cell response." (PMID 40125553, 2025). "Here, we show that Fgl2 is elevated in the setting of melanoma and is immunosuppressive to the T cell antitumor response." (PMID 40125553, 2025). "Using the gp100/pmel-17 B16 mouse model of melanoma where pmel-17 transgenic CD8+ T cells recognize the self-antigen gp100 on the murine melanoma cells, we found that the immunosuppressive effect of host Fgl2 was conserved." (PMID 40125553, 2025). "To investigate the presence of Fgl2 in patients ith skin cutaneous melanoma (SKCM) more broadly, we queried the expression of Fgl2 in patients with primary melanoma versus melanoma metastasis through the tumor immune estimation resource (TIMER) database." (PMID 40125553, 2025). "When challenged with B16 melanoma or LCMV-Clone 13, mice given Fgl2-deficient antigen-specific CD8+ T cells exhibited enhanced antitumor and antiviral response via increased persistence of antigen-specific CD8+ T cells." (PMID 38902261, 2024). "At the protein level, Fgl2 cytokine was induced in CD8+ TIL from digested melanoma patient tumor tissue upon stimulation with anti-CD3/CD28." (PMID 38902261, 2024). "Only 2/12 endometrial cancer and 1/11 melanoma samples are FGL2 positive detected by HPA021011 antibody, and all the samples are negative by HPA026682 antibody in the HPA database." (PMID 39629005, 2024). "Fgl2 is elevated in melanoma and is immunosuppressive to tumor-specific CD8+ T cells." (PMID 40125553, 2025). "We show that antigen-specific CD8+ cells bearing an exhaustion-related gene signature from mice as well as human TIL express robust levels of Fgl2, and this expression in melanoma patients is correlated with decreased patient survival during checkpoint inhibition." (PMID 38902261, 2024). "As such, these studies showed the therapeutic efficacy of antibodies blocking Fgl2, suggesting that this approach may hold clinical promise in melanoma." (PMID 38902261, 2024). "Similarly, FGL2 has been found to be overexpressed in certain cancers, including breast cancer, colon cancer, and melanoma, where it contributes to tumor growth and metastasis." (PMID 39629005, 2024). "After confirmation of a similar immune cell reconstitution between WT HSC– and Fgl2–/– HSC–reconstituted mice 8 weeks later, bone marrow chimeric mice were challenged with B16-F10 melanoma cells." (PMID 40125553, 2025). "Work herein shows that Fgl2 secreted by macrophages is a consequential binding partner of FcγRIIB on CD8+ T cells and functions during melanoma challenge to decrease tumor control through reducing the pool of tumor-specific CD8+ T cells." (PMID 40125553, 2025). "Using the B16 melanoma model, we found that FcγRIIB+ CD8+ also express significantly more Fgl2 at the protein level than FcγRIIB− CD8+ T cells." (PMID 38902261, 2024). "Based on our expertise in ovarian cancer we chose to study the role of FGL2 in epithelial ovarian cancer and expanded our study to compare and contrast the role of FGL2 in a common model for immunotherapy research, the B16F10 melanoma model." (PMID 38191799, 2024).
melanoma (continued). "The data herein are in agreement with recent work by others using the B16 model of melanoma that show that B16 cells are not a major cellular source of Fgl2 in mice." (PMID 40125553, 2025). "These mouse cancer cell lines do not express FGL2 in vitro (undetected by qPCR and ELISA) nor in vivo, in agreement with human ovarian cancer and melanoma." (PMID 38191799, 2024). "We tested two murine models of cancer in which the role of FGL2 has not been previously studied: epithelial ovarian cancer and melanoma." (PMID 38191799, 2024). "By querying scRNA-seq data of many human cancer types, including ovarian, melanoma, lung, breast and colorectal, we have shown that FGL2 is not expressed in cancer cells, but rather multiple immune and stromal cell types in the TME, with predominant expression in monocytes and macrophages." (PMID 38191799, 2024). "We first sought to determine whether the absence of FGL2 (Fgl2−/− mice) relieved immunosuppression and prolonged survival in melanoma and ovarian cancer models." (PMID 38191799, 2024).
autoimmune disease (3 papers, 2011 to 2024). A disorder resulting from loss of function or tissue destruction of an organ or multiple organs, arising from humoral or cellular immune responses of the individual to their own tissue constituents. "In autoimmune diseases, Tregs are recruited to the inflamed site and contribute to the expression of FGL2." (PMID 38816776, 2024). "We have demonstrated that FGL2 has a role in autoimmune disease based on the finding that fgl2−/− mice develop autoimmune glomerulonephritis." (PMID 26241231, 2015). "Here we discuss the important role of Treg and FGL2 in preventing alloimmune and autoimmune disease." (PMID 26241231, 2015). "Indeed, it has been reported that both FGL2 and PD-1 are expressed on T cells, macrophages, and DCs, and that targeted deletion of fgl2 or PD-1 leads to impaired T cell activity, and these events are related to the development of autoimmune diseases." (PMID 21750671, 2011). "Conversely, a complete lack of FGL2 can also be detrimental, as it may result in autoimmune diseases and acute rejection of xenografts, underscoring the significance of FGL2 in the body." (PMID 38816776, 2024).
B-Cell Lymphoma (3 papers, 2014 to 2021). "FGL2 expression increases in PBMCs of patients with active B-cell lymphomas but normalizes after remission." (PMID 28978925, 2017). "FGL-2 activity was determined in patients with B-cell lymphoma (n = 53), and healthy controls (n = 145)." (PMID 25303152, 2014). "The prothrombinase activity of FGL-2 was measured in PBMC by a thrombin generation assay of 53 patients with B-cell NHL and 145 healthy controls." (PMID 25303152, 2014). "This study aims to determine the prothrombinase activity of FGL-2 in peripheral blood mononuclear cells (PBMC) of patients with B-cell lymphoma." (PMID 25303152, 2014). "If our findings are confirmed by other studies, the assay of FGL-2 activity in PBMC could be used as a marker for follow up of B-cell lymphoma." (PMID 25303152, 2014). "In the present work we measured FGL-2 prothrombinase activity and mRNA expression in peripheral blood mononuclear cells (PBMC) of patients with B-cell lymphoma." (PMID 25303152, 2014).
colitis (3 papers, 2015 to 2018). Inflammation of the colon. "We also observed a constant pool of M1 macrophages within the lamina propria of inflamed gut tissue that was unexpectedly increased by loss of Fgl2, with concomitant aggravation of colitis." (PMID 29441068, 2018). "In this study, we sought to investigate the role of Fgl2 in the development of intestinal inflammation and colitis-associated colorectal cancer (CAC)." (PMID 29441068, 2018). "Here, we report that Fgl2 deficiency increased susceptibility to dextran sodium sulfate-induced colitis and CAC in a mouse model." (PMID 29441068, 2018). "The observation that depletion of Fgl2 leads to exacerbated colitis prompted us to investigate whether and how Fgl2 deficiency affects the development of CAC." (PMID 29441068, 2018). "Given the crucial role of innate immune cells in both the onset and resolution of inflammation in DSS-induced colitis and the regulatory functions of Fgl2 in various immune cells, we examined whether and how loss of Fgl2 impacts colonic innate immune cell infiltration." (PMID 29441068, 2018). "Thus, Fgl2 deficiency also promotes the inflammatory response in DSS-induced colitis." (PMID 29441068, 2018). "Next, we sought to further investigate the mechanism by which Fgl2 interferes with the progression of experimentally induced colitis." (PMID 29441068, 2018). "During colitis development, the expression of the membrane-bound and secreted forms of Fgl2 (mFgl2 and sFgl2, respectively) in the colon were increased and predominantly expressed by colonic macrophages." (PMID 29441068, 2018). "Here, we show that Fgl2 expression is significantly upregulated during DSS-induced mouse model of colitis, a widely used model that mimics the clinical features of human ulcerative colitis." (PMID 29441068, 2018). "A recent report implied that Tregs and effector T cells control intestinal homeostasis through expression of Fgl2 in a T cell-induced colitis model." (PMID 29441068, 2018). "To assess the significance of Fgl2 expression in colitis, we challenged Fgl2−/− and their WT littermates (controls) with DSS and then monitored their susceptibility to colitis." (PMID 29441068, 2018). "Taken together, these results demonstrate that Fgl2 is critical for suppressing DSS-induced colitis." (PMID 29441068, 2018). "Simultaneously, several genes whose products act to limit or resolve colitis [e.g., Areg and Fgl2 (blue dots)] showed lower expression levels in HIF-deficient macrophages." (PMID 30455703, 2018). "To address this issue, we investigated the contribution of Fgl2 to IBD development by evaluating its expression in the inflamed intestine and examining the effects of Fgl2 deficiency on dextran sodium sulfate (DSS)-induced colitis in mice." (PMID 29441068, 2018). "We found that Fgl2 is critical for limiting DSS-induced colitis and subsequent CAC development through its effects on macrophage polarization and might serve as a biomarker and/or therapeutic target in the treatment of IBD and other inflammatory diseases." (PMID 29441068, 2018). "In addition, using bone marrow chimeric mice, we determined that Fgl2 function in colitis is strictly related to its expression in the hematopoietic cells." (PMID 29441068, 2018). "Furthermore, we proved that Fgl2 function in colitis is related to its expression in BM-derived cells." (PMID 29441068, 2018). "We found that Treg from mice that ubiquitously overexpressed FGL2 (fgl2Tg mice) completely prevented T cell-mediated colitis, whereas wild-type Treg were only partially protective, and Treg from fgl2−/− mice were unable to prevent development of colitis (unpublished data)." (PMID 26241231, 2015). "Thus, loss of Fgl2 exacerbates the clinical and histological features of DSS-induced colitis." (PMID 29441068, 2018). "Thus, we next aimed to ascertain whether hematopoietic cell-derived Fgl2 exerts protective effect against DSS-induced colitis." (PMID 29441068, 2018).
colitis (continued). "As expected, Fgl2-deficient colonic macrophages isolated from DSS-treated mice produced higher levels of the M1 effector molecule IL-1β, but lower levels of the M2 polarization markers MR, Arg-1, and Fizz1 in DSS colitis than macrophages from DSS-treated WT mice." (PMID 29441068, 2018). "We found that Fgl2 is mainly expressed in colonic macrophages in colitis and suppresses DSS-induced colitis and subsequent CAC development." (PMID 29441068, 2018). "Together, these data suggest that Fgl2 is induced in the inflamed colon and that it is mostly expressed by various immune cells types, specially, macrophages, in DSS-induced colitis." (PMID 29441068, 2018). "In accordance with our observations in the colitis model, during each cycle of DSS challenge, Fgl2−/− mice lost more body weight than their WT littermates." (PMID 29441068, 2018). "Because activated macrophages can be polarized into M1 or M2 subtypes and modulating M1/M2 polarization can affect colitis severity, we wondered if macrophage polarization is perturbed in the absence of Fgl2." (PMID 29441068, 2018). "To date, experimental evidence is still lacking to address which cell type drives Fgl2 expression in intestinal inflammation, we found that colonic macrophages are the major source of both mFgl2 and sFgl2 in colitis." (PMID 29441068, 2018). "Furthermore, the suppression of Th1 and Th17 but not Th2 responses by TIGIT+ Treg was dependent on FGL2.21In vivo, FGL2 was critical in the control of effector T cell expansion by TIGIT+ Treg in lymphopenic hosts and in controlling a number of inflammatory diseases including colitis." (PMID 26241231, 2015). "Thus, at the early stage of DSS-induced colitis, increased M1 polarization and activation by Fgl2 depletion may contribute to the exacerbated colitis, whereas during the late phase of DSS colitis, suppression of M2 polarization may be additionally responsible for colitis aggravation." (PMID 29441068, 2018).
diabetes (3 papers, 2011 to 2020). "In a diabetes mouse model Fgl2 gene silencing inhibits apoptosis and improves heart function by probably modulating immune response." (PMID 32179820, 2020).
diabetic nephropathy (3 papers, 2011 to 2026). "In a murine model of diabetic kidney disease, FGL2 was increased in the glomerular and tubulointerstitial capillaries and associated with microthrombosis." (PMID 36671474, 2022). "Western blot analysis revealed that fgl2 protein expression in the diabetic rats began to increase from the 19th week during the development of diabetic nephropathy and was significantly elevated compared to the normal rats." (PMID 23554679, 2011). "In this study, we adopted an established rat model of type 2 diabetes to examine the expression of fgl2 in endothelial cells of the glomerular and tubulointerstitial capillaries and investigated the possible significance of fgl2 in diabetic nephropathy." (PMID 23554679, 2011). "Further studies are warranted to elucidate whether specifically inhibiting fgl2 activation or downregulating fgl2 expression could delay the progression of diabetic nephropathy." (PMID 23554679, 2011). "However, little knowledge is available about fgl2 in diabetic nephropathy." (PMID 23554679, 2011). "Our RT-PCR and immunoblotting analysis showed that fgl2 mRNA and protein levels were increased in microvascular endothelial cells of the glomeruli and renal interstitia at week 19 and became significantly elevated with the development of diabetic nephropathy (P < 0.01)." (PMID 23554679, 2011).
endometriosis (3 papers, 2021 to 2024). The growth of functional endometrial tissue in anatomic sites outside the uterine body. "Both cytokines regulate Fibrinogen‐like protein 2 (FGL2) expression, and peritoneal fluid Tregs of endometriosis patients also have increased FGL2 expression." (PMID 36746607, 2023). "Collectively, these data show that FGL2 secreted by Tregs can function as an important factor in endometriosis progression through direct and indirect regulation of the immune functions of macrophages and T cells." (PMID 33893391, 2021). "While the importance of FGL2 for numerous diseases has been established, much less is known about the role of FGL2 in endometriosis." (PMID 33893391, 2021). "FGL2 drives macrophage polarization toward the pro‐repair phenotype highlighting a potential positive feedback loop between T cells and macrophages that drives endometriosis progression." (PMID 36746607, 2023). "We propose that during stage I-II endometriosis, pelvic inflammatory cytokines may induce FGL2 production in Tregs." (PMID 33893391, 2021). "Consistent with higher sFGL2 concentrations found in peritoneal fluid of patients with endometriosis, FGL2 expression in eutopic endometrium increased compared to that of the normal endometrium, and even higher expression levels were found in endometriotic lesions (ovarian endometriosis)." (PMID 33893391, 2021). "Tregs are the main source of FGL2 in peritoneal fluid of women with endometriosis." (PMID 33893391, 2021). "The current study focused on identifying whether FGL2 is a key effector molecule of Tregs involved in the pathogenesis of endometriosis." (PMID 33893391, 2021). "We also detected FGL2 levels of individual immune cell populations from peritoneal fluid of women with or without endometriosis and we found that Tregs in peritoneal fluid of endometriosis patients secreted significantly higher levels of FGL2 than that of control." (PMID 33893391, 2021). "Targeting Tregs/FGL2 may constitute a viable therapeutic approach to treating endometriosis." (PMID 33893391, 2021). "The FGL2-induced pro-repair macrophages further promote Th2 and Tregs differentiation, which alters the balance between pro- and anti-inflammatory microenvironments in endometriosis and facilitates the formation of immune tolerance in stage III-IV endometriosis." (PMID 33893391, 2021).